IL6 (interleukin 6)
Diseases named in the same sentence as IL6 in open-access papers (continued):
Sharing a sentence is not in itself a finding about the gene and the disease.
cancer (continued). "Some researchers focused on the development of delivery systems that combine silencing of inhibitor of apoptosis (IAP) genes BV6 (their increased expression is associated with cancer progression and chemoresistance) and interleukin (IL)-6, as a new promising anti-tumor treatment strategy." (PMID 34502560, 2021). "Meta-analysis of the IL-6 -174G/C polymorphism association with cancer risk." (PMID 33684135, 2021). "Additionally, recent data support the role of several SNPs in IL-6 (Interleukin 6) gene (rs1800795, rs1800796 and rs1800797) as biomarkers of an increased cancer risk in several tumors." (PMID 35095996, 2021). "Meta-analysis of the IL-6 -572G/C polymorphism association with cancer risk." (PMID 33684135, 2021). "Numerous molecules such as tumor necrosis factor (TNF)-α, interleukin-1 (IL-1) and IL-6 are common biomarkers of inflammation associated with cancer, and they could be regulated by the transcription factor NF-κB." (PMID 35096970, 2021). "Similarly, elevated IL-6 serum levels were shown to be associated with a poorer prognosis in various cancer entities." (PMID 34064969, 2021). "Also, interleukin 6 (IL-6) is another biomarker that has been reported to be associated with the prognosis of cancer patients." (PMID 34239594, 2021). "Moreover, STAT3 activation through IL-6/IL-11 in cancer associated fibroblasts (CAFs) promoted CRC development and poor prognosis." (PMID 34046355, 2021). "However, the mechanisms underlying IL-6 leading to chemotherapy resistance in cancers have remains elusive." (PMID 34131122, 2021). "In addition, HCC-derived cancer-associated fibroblast contributes to the production of PD-L1+ neutrophils by IL-6, impairing the T-cell function and fostering immunosuppression." (PMID 33679751, 2021). "This shock also leads to the activation of inflammation dominated by IL-6 and associated inflammatory network to reprogram both cancer cells and the stroma cells and creates microenvironment to promote the growth of newly reprogrammed daughter cells for the resistance and disease relapse." (PMID 34588424, 2021). "Meta-analysis of the IL-6 -597G/A polymorphism association with cancer risk." (PMID 33684135, 2021). "Furthermore, the c-Myc cofactor PIM1 was identified as an IL-6/STAT3 downstream mediator of the acquisition of EMT and CSC-associated features in cancer cells, suggesting a role for c-Myc on IL-6/OSM-promoted EMP." (PMID 34361105, 2021). "Indeed, chronic inflammation has been demonstrated to lead to JAK/STAT pathway mutations in other cancers, and upregulation of interleukin-6-mediated STAT3 activation has been reported in BIA-ALCL cell lines." (PMID 34638403, 2021). "Additionally, a number of the CpG sites included in the predictor have previously been associated with gestational age and carcinoma, both of which have also been associated with IL-6 levels and regulation." (PMID 33595649, 2021). "IL-6 has been implicated as a core mediator of cancer cachexia." (PMID 33329046, 2020). "Moreover, increased IL-6 serum levels are associated with poor prognosis in several types of cancer, including AML." (PMID 32150944, 2020). "In fact, leptin signaling is linked to the development of several cancer types, including pancreatic cancer, through different mechanisms including the production of inflammatory factors (IL-1, IL-6, and TNF-α), which have been shown to promote tumor invasion and metastasis." (PMID 32604970, 2020). "Cancer pain is closely associated with IKKβ/NF-κB, IL-1β, IL-6, and TNF-α." (PMID 32431607, 2020). "One significant example of this crosstalk between cancer cells and the microenvironment is the secretion of cytokines like interleukin-6 (IL-6) by the cancer-associated mesenchymal stem cells that enhance the progression of CRC through the IL-6/JAK2/STAT3 signaling." (PMID 32626705, 2020).
cancer (continued). "Transcript levels of soluble factors often linked to cancer-promoting (CP) inflammation, such as IL-6, CXCL1, CXCL2, IL-1β, or G-CSF, were markedly higher in COX-competent compared to COX-deficient tumors, and their expression was unchanged in the absence of NK cells." (PMID 33220234, 2020). "Cancer-associated muscle wasting is associated with decreased expression PGC1α, which may be mediated by IL-6." (PMID 33291708, 2020). "Thus, cancer-associated macrophages can secrete various cytokines (e.g., TGFβ, IL-6) that induce the conversion of cancer cells to cells with CSC phenotype and contribute to chronic inflammation in tumor region." (PMID 33415069, 2020). "It has been reported that cancer associated adipocytes secrete IL-6 and TNF-α." (PMID 32796516, 2020). "In addition, high levels of IL-6 have been associated with cancer cachexia progression and worsening and correlated with loss of body mass, as well as reduced amounts of adipose tissue." (PMID 32660156, 2020). "Weight loss and survival rates are correlated with IL-6 levels in cancer patients." (PMID 32934774, 2020). "Such crosstalk could potentially contribute to a higher IL‐6 secretion than what can be caused by the transformed cancer cells themselves." (PMID 31436048, 2020). "In two patients the peak of S100B occurred 14 days after the observed peak of IL-6 which might suggest that IL-6 reflects immune activation but may not be implicated in the local anticancer immune reaction within the cancer tissue." (PMID 32188047, 2020). "Additionally, C-reactive protein (CRP) and interleukin 6 (IL-6), other serum inflammatory markers, have shown their possibilities as posttreatment prognostic monitoring factors for predicting the risk of cancer recurrence and patient death." (PMID 32300189, 2020). "While we have observed that YB-1 influences VEGF, our observation of the communication of cancer-associated fibroblasts (CAFs) with the overexpression of interleukin (IL-6), Il-8, RANTES, and VEGF needs to be further evaluated in light of data showing the involvement of YB-1." (PMID 31947591, 2020). "While classic IL-6 signaling is associated with anti-inflammatory properties, trans-signaling has been shown to have a pro-inflammatory effect and play a major role in the development of cancer." (PMID 33143292, 2020). "Moreover, recent in vitro data suggest that E6 and E7 oncoproteins and spliced isoforms of E6 oncoprotein would be associated with higher levels of IL6, responsible of an immunosuppressive environment within cancer." (PMID 33042820, 2020). "Anorexia in cancer patients is associated with the predominance of signals suppressing appetite in the hypothalamus—proopiomelanocortin and anorexigenic action of pro-inflammatory cytokines: IL-1α, IL-1β, IL-6, TNF-α." (PMID 33158194, 2020). "Fib, Alb and pAlb were the acute phase reaction proteins in response to the chronic inflammation, IL-6 secreted by cancer-associated fibroblast and cancer cell could inhibit pAlb and stimulate Fib, eventually leading to low pAlb and elevated Fib." (PMID 30897064, 2019). "Further, activation of STAT3 downstream of IL6 has been linked to muscle wasting in cancer." (PMID 31058816, 2019). "In addition, while baseline IL-6 was associated with higher cancer mortality overall and among African-Americans and Whites in this study, the association between IL-10 and cancer mortality remained significant only among Whites in our study." (PMID 31448052, 2019). "Indeed, Xing and collaborators recently demonstrated that IL-6 silencing causes increasing of apoptosis, thus reducing tumorigenicity of cancer cells." (PMID 31191652, 2019). "Like IL-6, it has been shown that the expression of IL-4 and IL-10 is associated with cancer 87-89." (PMID 31602271, 2019). "Of these, IL-6 has been implicated as the key cytokine involved in chronic inflammation in cancer." (PMID 31252615, 2019).
cancer (continued). "In crude models, every unit increase in log-transformed IL-6 was associated with a 3-fold higher risk of cancer mortality (HR: 3.15, 95% CI: 2.11–4.72) and a more than 4-fold higher risk of cancer mortality comparing the 3rd vs. 1st tertile (HR: 4.41, 95% CI: 2.45–7.95)." (PMID 31448052, 2019). "Downregulation of let-7 by cancer-associated MSCs upregulates IL-6 expression." (PMID 31915680, 2019). "IL-6 is often found upregulated in cancer and has been associated with the tumourigenic process." (PMID 31906092, 2019). "Increased IL-6 levels in the patients’ sera are indeed associated with dramatic changes in the metabolism of cancer patients because it influences the metabolism of adipocytes, hepatocytes and striated muscle cells, and eventually induces cancer cachexia and wasting." (PMID 30925774, 2019). "The serum IL-6 was also measured as the biomarker of cancer-associated cachexia." (PMID 31073508, 2019). "Multispecific antibodies targeting TAMs, CD59, IL-6 and targetable cancer mutations might be a new promising strategy for cancer immunotherapy." (PMID 31685825, 2019). "Indeed, the poor outcome of many cancer patients is closely associated with elevated serum levels of IL-6." (PMID 31769418, 2019). "Besides IL-1, IL-6, and IL-8, other proinflammatory factors are also associated with the occurrence and development of cancer, such as TNF-α, TGF-β, BCA-1, and so on." (PMID 31832112, 2019). "We first used IL-6 whole body KO (IL-6−/−) mice, in which mice lack the complete production of systemic IL-6, an upstream regulator previously implicated in both burn and cancer-induced WAT browning." (PMID 31740668, 2019). "The muscle loss in cancer cachexia is directly or indirectly linked to overexpression of IL-6." (PMID 30426026, 2018). "However, there are many unsolved problems associated with the routine measurement of IL-6 in cancer patients, including its high cost and inconvenience." (PMID 28744596, 2018). "However, when cardiovascular disease, cancers and other conditions were taken into account, the magnitude of the association between age and circulating IL-6 decreased substantially but remained statistically significant in men." (PMID 29951282, 2018). "While MDM2 inhibitors are currently in clinical trials as primary cancer therapeutics, the loss of senescence-associated IL-6 secretion suggests they may also be useful as adjuvants to senescence-inducing chemotherapies." (PMID 29402901, 2018). "The activation of these pathways mediated by IL-6 as well as the associated increased degradation and low availability of amino acids may also contribute to defective erythropoiesis in advanced cancer patients." (PMID 30294279, 2018). "Given that PC patients have the highest frequency of weight loss than those with other common cancers, our primary objective in this study was to explore the association of CC status with the serum IL-1β, IL-6, IL-8, or TNF-α levels in patients with resected or locally advanced PC." (PMID 30513776, 2018). "Preadipocytes exhibited in an increased IL-6 secretion and cancer-associated fibroblast markers expression, FSP1 and α-SMC in co-culture with MCF10DCIS.com or in MCF10DCIS.com conditioned media, whereas the adipocyte differentiation capacity was suppressed by co-culture with MCF10DCIS.com." (PMID 30134951, 2018). "Twelve studies reported the association between IL-6 promoter polymorphisms and cancer prognosis." (PMID 29552316, 2018). "Furthermore, studies have also noted differences in disease prognosis based on the expression levels of various cytokines in numerous cancers, where higher levels of interleukin-6 and interleukin-10 were associated with poorer outcomes." (PMID 29298730, 2018). "A high IL-6 level is generally associated with a poorer outcome, particularly regarding renal cell, ovarian and prostate cancer, and correlated to more severe symptoms in regards to cancer as well as the development of anti-cancer drug resistance." (PMID 30038723, 2018).
cancer (continued). "High serum IL-6 levels in a subject with weight loss and fatigue, but without any signs of infections or inflammatory disease, would suggest a need for a CT-scan, since the risk of cancer is high if serum IL-6 is very high." (PMID 30038723, 2018). "Similarly to IL-6, clinical studies have linked high serum levels of IL-8 to disease progression of various cancer types." (PMID 29946544, 2018). "However, previous studies on the association of IL-6 promoter polymorphisms with predisposition to different cancer types are somewhat contradictory." (PMID 29552316, 2018). "In addition, when the three promising inflammatory biomarkers (α1-acid glycoprotein, C-reactive protein and IL-6) were considered together, IL-6 was the only one that remained associated with mortality by cancer." (PMID 29951282, 2018). "To confirm whether IL-6 promoter polymorphisms are related to cancer risk, we performed this meta-analysis, aiming to measure the correlation between IL-6 promoter polymorphisms and cancer susceptibility and prognosis." (PMID 29552316, 2018). "Therefore, we performed this meta-analysis regarding the relationship between IL-6 promoter single nucleotide polymorphisms and cancer susceptibility and prognosis." (PMID 29552316, 2018). "Furthermore, IL-6 promoter polymorphisms were significantly associated with the prognosis of cancer." (PMID 29552316, 2018). "IL-6 and leptin have been shown to be indispensable for the proliferation, metastasis and initiation of cancer and are significantly associated with poor prognosis in human cancers." (PMID 30563531, 2018). "IL-6 expression of cancer tissues was associated with advanced clinical T stage." (PMID 29296206, 2017). "TNF and IL6 have been well defined as inflammatory cytokines in cancer-associated inflammation." (PMID 28467300, 2017). "Strikingly, our data also suggests that this synergistic IL-6/8 paracrine pathway-mediated enhancement of cell migration is an adaptive process dictated by cell signalling and differs from the mechanism associated with cancer-stem-cell (CSC)." (PMID 28548090, 2017). "Further, despite the absence of adaptive immunity, splenic tissue from orthotopically engrafted mice demonstrated elevations in several pro-inflammatory cytokines associated with cancer cachexia, including TNFα, IL1β, IL6 and KC (murine IL8 homologue), when compared to controls." (PMID 27901481, 2017). "In summary, our results suggest a role for IL6-174G>C polymorphism in cancer prognosis." (PMID 28548958, 2017). "Cancer susceptibility and severity may be associated with functional polymorphisms of cytokine genes involved in regulating inflammation; in particular, polymorphisms of IL-6 and IL-10 genes may influence cancer susceptibility and in some cases its prognosis." (PMID 28075340, 2017). "Besides IL-6, which was described as marker of both cancer-associated and cancer treatment-induced inflammation, studies of other cytokines were less frequently reported." (PMID 28377717, 2017). "Further, elevated CRP and IL-6 are associated with CACS in advanced cancer." (PMID 28384249, 2017). "MiR-21 is an important cancer risk factor whose expression is induced by IL-6." (PMID 28467474, 2017). "The study conducted by Meyers demonstrated that at baseline, higher IL-6 levels were associated with poorer executive functions, confirming that cancers are associated with high levels of circulating cytokines, connected with cognitive dysfunction, before chemotherapy." (PMID 28377717, 2017). "Furthermore, IL-6 levels are frequently found elevated in cancer patients with an association to weight loss and shorter survival." (PMID 28515477, 2017). "IL-6 and IL-8 are multifunctional chemokines associated with reactive stroma and which may play widespread and causative roles in cancer progression." (PMID 29245949, 2017). "Our results indicate that there might be a connection between IL-6 polymorphism and OS in patients with cancer." (PMID 28548958, 2017).
cancer (continued). "reduced IL-6 secreted by CAFs(cancer associated fibroblasts)." (PMID 29254283, 2017). "The cytokines IL-6 and IL-10 are associated with poor prognosis in all types of cancer." (PMID 28337150, 2017). "The fact that IL-6 has been associated to an angiogenic gene program in pericytes and even affects pericytes proliferation during angiogenesis in cancer, supports our data and might also explain why we observed a reduced proliferation of GBC-PC in vitro." (PMID 28978142, 2017). "Third, there are several SNPs in IL-6 which reported to be correlated to cancer risk or survival." (PMID 28548958, 2017). "Elevated IL-6 levels in human serum are associated with increased cancer risk." (PMID 28030810, 2017). "Interleukin-6 (IL-6), a pro-inflammatory cytokines in host defense against inflammation and tissue injury, has been linked to tumorigenesis, angiogenesis, and survival in malignant tumors like GBM." (PMID 27285760, 2016). "Although the activation of the JAK-STAT signal by IL6 was observed in cancer, there have been few studies for the association between conjunctival epithelial cells and IL6, especially about the role of increased IL6 in a hyperosmolar state of conjunctival epithelial cells." (PMID 27555966, 2016). "Notably, the use of IL‐6 receptor antagonists or monoclonal antibodies directed against IL‐6 has been shown to dramatically inhibit the development of cancer‐associated muscle wasting and cachexia." (PMID 26811258, 2016). "Many experimental studies have suggested that similar to cancer-associated fibroblasts, myofibroblasts promote cancer progression and metastasis by expressing high levels of inflammatory factors and chemokines, such as interleukin-6 and C-X-C motif chemokine." (PMID 27459365, 2016). "Interleukin-6 (IL-6) is an important pro-inflammatory cytokine produced particularly by macrophages but also by other stromal cells such as neutrophils, cancer-associated fibroblasts and endothelial cells, as well as some cancer cells." (PMID 27738330, 2016). "Thus, potent inhibitory activity of this Comp against IL-6 production warrants further research concerning potential uses of Comp for anti-inflammatory diseases and inflammation-associated cancer." (PMID 27153074, 2016). "IL-6 signal cascade is triggered by IL-6/IL-6R complex via membrane-bound receptor and a soluble form of the IL-6R, which is frequently associated with inflammatory diseases and increased risk of cancers." (PMID 26745884, 2016). "Tumor-derived secreted factors such as TGF-β1, bFGF, and IL-6, have been shown to control the activation of cancer associated fibroblasts (CAFs), and the proteome/secretome of these CAFs, including hepatocyte growth factor (HGF), has been found to enhance the invasiveness of cancer cells." (PMID 27793046, 2016). "In keeping with this concept, transcripts encoding IL-6 and IL-11, key cytokines involved in inflammation-associated Stat3 activation in cancer, were marginally elevated after one week of GLI2A expression but highly induced by 2 and 3 weeks, when Stat3 activation is widespread." (PMID 26859571, 2016). "As IL-1β has also been linked to the expression of other cancer-associated cytokines, we tested the impact of miR-7-5p or si-RelA on expression of IL-6 and IL-8, and found that both miR-7-5p and si-RelA reduced the levels of secreted and intracellular IL-6 and IL-8." (PMID 27203220, 2016). "Interleukin-6 (IL-6) plays a contributory role in the progression and severity of many forms of cancer; it however remains unclear whether the relevance between circulating IL-6 and cancer is causal." (PMID 26096712, 2015). "For instance, IL-6 secreted by cancer cells drives the activation of normal fibroblasts toward becoming cancer-associated fibroblasts (CAF) that in turn elicit an EMT response in cancer cells and increases the CSC population." (PMID 26258068, 2015).